FBXO32 (F-box protein 32)
Description:
Substrate recognition component of a SCF (SKP1-CUL1-F-box protein) E3 ubiquitin-protein ligase complex which mediates the ubiquitination and subsequent proteasomal degradation of target proteins. Probably recognizes and binds to phosphorylated target proteins during skeletal muscle atrophy. Recognizes TERF1. Negatively regulates macrophage efferocytosis by promoting the ubiquitination of the transcription factor KLF4, suppressing the receptor tyrosine kinase MERTK transcription (By similarity). Regulates LPS-induced apoptosis and mitochondrial dysfunction through ANXA1 ubiquitination and degradation (By similarity). Mediates cyclin D1 protein stabilization via 'Lys-27'-linked ubiquitination.
Synonyms: MAFbx; ATROGIN1; Fbx32
Tractability: PROTAC: ubiquitination databases record sites on it.
Gene: Protein-coding gene on chromosome 8 (123,497,889 to 123,541,273, reverse strand). Ensembl gene ENSG00000156804.
Subcellular location: Cytoplasm; Nucleus
Subcellular location (Human Protein Atlas): Cytosol; Nucleoplasm
Pathways (Reactome):
Gene expression (Transcription): FOXO-mediated transcription of oxidative stress, metabolic and neuronal genes
Immune System: Antigen processing: Ubiquitination & Proteasome degradation
Metabolism of proteins: Neddylation
Gene Ontology:
Molecular function: protein binding; ubiquitin-like ligase-substrate adaptor activity
Biological process: negative regulation of SCF-dependent proteasomal ubiquitin-dependent catabolic process; protein ubiquitination; response to denervation involved in regulation of muscle adaptation; SCF-dependent proteasomal ubiquitin-dependent protein catabolic process
Cellular component: cytoplasm; cytosol; nucleoplasm; nucleus; SCF ubiquitin ligase complex; Z disc
Genetic constraint (gnomAD): Loss-of-function variants: 13 observed, 38.29 expected, observed/expected ratio (o/e) 0.34, 90% interval 0.22 to 0.54. The upper end of that interval is the gene's LOEUF score, 0.54, which puts it in group 2 of 6, group 1 being the genes least tolerant of losing a copy. Missense variants: 263 observed, 387.96 expected, observed/expected ratio (o/e) 0.68, 90% interval 0.61 to 0.75. Synonymous variants: 141 observed, 155.72 expected, observed/expected ratio (o/e) 0.91, 90% interval 0.79 to 1.04.
Gene-disease validity (ClinGen):
ClinGen rates the evidence that FBXO32 causes each of these diseases.
dilated cardiomyopathy (autosomal recessive): Limited. Cardiomyopathy which is characterized by dilation and contractile dysfunction of the left and right ventricles.
Homologues: Orthologues: chimpanzee FBXO32 (99% identical), macaque FBXO32 (99% identical), pig FBXO32 (99% identical), dog FBXO32 (99% identical), guinea pig FBXO32 (97% identical), mouse Fbxo32 (97% identical), rat Fbxo32 (95% identical), rabbit FBXO32 (92% identical), tropical clawed frog fbxo32 (82% identical), zebrafish fbxo32 (76% identical), Drosophila melanogaster CG11658 (29% identical), Caenorhabditis elegans mfb-1 (28% identical). Paralogues in human: FBXO25 (61% identical).
Diseases named in the same sentence as FBXO32 in open-access papers:
FBXO32 is named in the same sentence as 130 diseases in open-access papers, as found by Europe PMC text mining. Sharing a sentence is not in itself a finding about the gene and the disease. The quoted sentences say what the papers report.
muscle atrophy (147 papers, 2006 to 2026). The loss of muscle tissue due to inactivity or disease. "One of the transcripts with the highest module membership in the blue module is FBXO32, which encodes the protein atrogin‐1, an E3 ubiquitin ligase well recognized to be associated with muscle atrophy and cachexia." (PMID 38649783, 2024). "Muscle atrophy causes apparent muscle degradation, and the tripartite motif containing 63 (Trim63) and F-box only protein 32 (Fbxo32) are the most intensively studied E3 ubiquitin-protein ligases and are upregulated in atrophy models." (PMID 36139912, 2022). "Mice deficient for MuRF1/Trim63 and atrogin-1/Fbxo32 are protected against various forms of muscle atrophy and pharmacological inhibition of MuRF1 has been shown to attenuate muscle atrophy." (PMID 35615361, 2022). "Muscle atrophy signaling pathways have been well-documented, and one of the atrogenes (i.e., Fbxo32/MAFbx32/Atrogin-1) was significantly activated by BTX treatment in this study." (PMID 37717026, 2023). "For instance, animal models of muscle atrophy demonstrated a consistent increase in the gene expression of FBXO32 (ATROGIN1) and TRIM63 (MURF1), which are part of the ubiquitin proteasome pathway involved in protein degradation." (PMID 31498843, 2019). "In denervation-induced muscle atrophy, Fbxo32 mRNA level rises acutely after denervation, but returns to basal levels by day 14 despite persistent increase in FoxO3 activity." (PMID 28170423, 2017). "Experimental studies have associated increased expression of the pro-apoptotic ubiquitin proteasome E-3 ligases MuRF1 (aka TRIM 63) and MAFbx (aka Atrogin-1 or Fbxo32) with statin myalgia and muscle atrophy." (PMID 28771594, 2017). "In particular, increased levels of protein degradation-related markers such as muscle RING Finger 1 (MuRF-1) and F-box only protein 32 (Fbxo32, also known as Muscle Atrophy F-box) contribute to the occurrence of sarcopenia by elevating degradation, leading to muscle atrophy." (PMID 40724603, 2025). "Furthermore, their downstream genes such as FBXO32, TRIM63, CTSL, and BNIP3, which have been associated with skeletal muscle atrophy in humans and mice, were found to be significantly upregulated in G. parasuis-infected skeletal muscle." (PMID 38540418, 2024). "Well-accepted ‘atrogenes’, Atrogin-1 (Fbxo32) and Murf1 (Trim63) encoding muscle atrophy F-Box/atrogin-1 (MAFbx) and muscle-specific RING-finger protein 1 (MuRF1) belonging to ubiquitin–proteasomal pathway, are highly expressed in multiple models of muscle atrophy both in mRNA and protein levels." (PMID 35725651, 2022). "Our results demonstrate that increases in the mRNA levels of Fbxo32 and Trim63 E3 ligases are sufficient to manifest a reduction in the CSA, the gold standard for detecting muscle atrophy." (PMID 40331994, 2025). "We conducted an immunohistochemical analysis to evaluate the immunoreactivities of anti-FBXO32, anti-TRIM63, and anti-FoxO3a markers involved in diabetic skeletal muscle atrophy." (PMID 38020198, 2023).
Atrophy (121 papers, 2005 to 2026). Any weakening or degeneration, especially through lack of use. "Their expressions are increased transcriptionally under various atrophy conditions, and mice deficient in either MuRF1/Trim63 or atrogin-1/Fbxo32 were observed to be resistant to atrophy." (PMID 35276908, 2022). "In UPS, the most well-known ubiquitin enzymes associated with muscle atrophy are two E3 ubiquitin-protein ligases, TRIM63 (Tripartite Motif Containing 63, or MuRF1), and FBXO32 (F-box only protein 32, or atrogin 1)." (PMID 35891702, 2022). "Our results suggest that the activation of the Fbxo32 and Trim63 transcription can be achieved by different combinations of activators and co-activators in response to distinct atrophy stimuli." (PMID 29717119, 2018). "We also highlight the differential regulation of FBXO32 between the radiation group and the induced torpor groups, which might have implications in torpor-related protection against muscle atrophy." (PMID 37408201, 2023). "However, we found that atrophy-related genes (e.g., Trim63 and Fbxo32) were highly expressed in the adult synaptic region compared with the P0 synaptic region." (PMID 33933147, 2021). "To define whether the reduced size of the Sam68−/− fibers is accompanied by features of atrophy, we analyzed the expression levels of two atrophy-related genes: the ubiquitin ligases Fbxo32 (MAFbx/atrogin-1) and Trim63 (muscle RING-finger 1, MuRF1)." (PMID 32753528, 2020). "Three key mRNAs in muscle loss are muscle RING finger-1 (MuRF1, also called Trim63), muscle atrophy F-box (MAFbx, also called Fbxo32 and Atrogin-1), and Caspase 3, all upregulated in numerous rodent models of muscular atrophy including disease, immobilization, hind limb unloading, and spaceflight." (PMID 30906768, 2019). "A further feature reported in a number of different models of diseases resulting in muscle atrophy is the substantial up-regulation of two E3 ubiquitin ligases, atrogin-1/MAFbx (FBXO32) and MuRF1 (TRIM63), which are generally induced early during the atrophy process." (PMID 19400950, 2009). "For example, animal models of muscle atrophy demonstrated a consistent increase in expression of FBXO32 and TRIM63 but the same results have not been consistently confirmed in human studies." (PMID 31498843, 2019).
Cachexia (90 papers, 2005 to 2026). Severe weight loss, wasting of muscle, loss of appetite, and general debility related to a chronic disease. "To further validate cachexia development using established molecular markers of muscle wasting, we examined the expression of genes that encode ubiquitin ligases associated with muscle proteolysis (Trim63/MuRF1, Fbxo32/MAFBx, Fbxo31, Fbxo30/Musa1)." (PMID 31861290, 2019). "The ubiquitin ligases Trim63 and Fbxo32, which are associated with inflammation-induced muscle atrophy and cachexia, remained within normal levels, suggesting that the induction of the autophagocytic pathway was specific to mitochondria rather than a general increase in the catabolic pathway." (PMID 29127187, 2018). "Imperatorin is another promising agent to treat muscle loss in the context of cachexia, as it selectively inhibits the Stat3 (signal transducer and activator of transcription 3)-dependent atrophy-signaling pathway, by downregulating skeletal muscle atrogene expression, such as Fbxo32." (PMID 33114658, 2020). "Then qPCR of muscle RNA showed reduced expression of Fbxo32 and Murf1 in the cachexia model mice fed the inulin diet." (PMID 41305932, 2025). "Paradoxically, KD did not reverse the increased expression of atrophy markers Trim63, Foxo1 and Fbxo32 in gastrocnemius muscle, which suggests that ketones exert pro‐anabolic effects even in the presence of increased catabolism in cachexia." (PMID 38632714, 2024). "Representative UPS proteins, such as MAFbx/Fbxo32 and MuRF1/Trim63, have been shown to be highly active in cancer cachexia." (PMID 39624846, 2024). "On the molecular level, cachexia is often determined through the assessment of muscle atrogenes, most prominently Atrogin 1 (F-Box Protein 32/Fbxo32) and MuRF1 (Muscle-Specific RING Finger Protein 1, also called Tripartite Motif Containing 63/Trim63)." (PMID 35008253, 2021). "Clinically, patients presenting cachexia or muscle wasting due to denervation or immobilization show increased expression of Fbxo32." (PMID 33114658, 2020). "Ubiquitin E3 ligases, Fbxo32/atrogin‐1/Mafbx and Trim63/MuRF1, were increased in the diaphragm at the time of cachexia onset (D12), supporting their involvement in muscle fibre atrophy, but declined thereafter, showing significant transcriptional repression at endpoint." (PMID 39810606, 2025). "In the current study we used qRT-PCR to measure components of these pathways, as well as the atrophy biomarkers atrogin-1/Fbxo32 and MuRF1/Trim63, to determine whether the response of muscle to human PC cells is similar to syngeneic murine models of cancer cachexia." (PMID 27901481, 2017). "Trim63 and Fbxo32 expression was increased by 2.3 fold and 1.4 fold, respectively, in CT26-bearing cachexia mice without IDH1 mutation." (PMID 37741882, 2023). "Because no clear patterns of gene expression emerged based on disease, we conclude that the type of disease does not dictate direction of change for FBXO32 or TRIM63 in the context of cachexia/sarcopenia." (PMID 31498843, 2019). "The up-regulation of UBB, FBXO32 (atrogin-1) and TRIM63 (MuRF1) in the irradiated and cachectic muscle tissue suggested that radiation-induced cachexia may share a similar pathway to other muscular atrophic conditions." (PMID 27029502, 2016). "Importantly, neither Fbxo32/atrogin 1 nor MuRF1 were induced in the non‐atrophying TA of breast cancer 4T1‐bearing mice that did not present cachexia." (PMID 35611892, 2022).
sarcopenia (78 papers, 2009 to 2026). Progressive decline in muscle mass due to aging which results in decreased functional capacity of muscles. "We used a gain-of-function strategy with a molecule that has been shown to be necessary and sufficient to induce muscle atrophy and a sarcopenia phenotype in mammals: Atrogin-1 (also named Fbxo32)." (PMID 41511973, 2026). "These cytokines, viz., IL-6, TNF-α, and IL-1β, activate muscle-specific protein degradation pathways through E3 ubiquitin ligases TRIM63 and FBXO32, linking NSCLC progression to cancer-associated sarcopenia." (PMID 42278237, 2026). "FBXO32 is critically involved in the ubiquitin-driven degradation of proteins in SkM during sarcopenia (." (PMID 33182325, 2020). "Here we identified Dkk3 as the key secreted factor generated by muscles to induce sarcopenia and characterized the mechanism of Dkk3-dependent transcription activation of Fbxo32 and Trim63." (PMID 29717119, 2018). "Interestingly, Fbxo32 (Atrogin-1; Mafbx) has been shown to be upregulated in sarcopenia." (PMID 29651131, 2018). "E3ubiquitin–protein ligase is the rate-limiting enzyme for the polyubiquitinationof protein substrates, and its most relevant to sarcopenia are tripartitemotif-containing 63 (TRIM63) and F-box only protein 32 (FBXO32)." (PMID 39077715, 2022). "MAFbx/Atrogin1/Fbxo32 was not upregulated during sarcopenia in the mouse or the rat, which is in agreement with our earlier observations." (PMID 37438807, 2023). "Interestingly, MAFbx/Atrogin1/FbxO32 was not upregulated during sarcopenia in the mouse or the rat, distinguishing sarcopenia from more acute settings of atrophy." (PMID 37438807, 2023). "Of note, no consistent results in the expression of FBXO32 and TRIM63, rather not increased, have been obtained in studies of human sarcopenia, suggesting that sarcopenia may be developed through different pathways from the relatively acute muscular atrophy." (PMID 40623060, 2025).
muscular atrophy (74 papers, 2009 to 2026). "MuRF1 and Atrogin1 are muscle-specific ubiquitin ligases encoded by Trim63 and Fbxo32, respectively, and are recognized as representative biomarkers of muscular atrophy." (PMID 37049603, 2023). "We found that 6- and 4.8-fold upregulation, respectively, of Fbxo32 and Trim63 was sufficient to reduce the ES to −3.89 (95% CI: −4.45 to −3.32) for the muscle fiber cross-sectional area and the development of skeletal muscle atrophy." (PMID 40331994, 2025). "Studies have shown that Fbxo32, an important transcription factor, is an important marker reflecting muscular atrophy." (PMID 38784031, 2024). "As expected, GA suppressed the Dex-induced increase in the expression of Trim63 and Fbxo32, muscle-specific ubiquitin ligase genes involved in muscular atrophy." (PMID 37049603, 2023). "Our investigation of STZ-induced skeletal muscle atrophy revealed that the expression of FBXO32, TRIM63, and FoxO3a genes was more significant in fast-twitch muscle fibers (EDL) than in slow-twitch muscle fibers (soleus)." (PMID 38020198, 2023). "We also included ERRFI1, which encodes for a negative regulator of the RTK signalling, and the E3 ligase FBXO32/Mafbx/Atrogin1, involved in muscular atrophy." (PMID 31081251, 2019). "However, only high-dose AM was able to improve gastrocnemius muscle atrophy in the model mice, with Coll, MSTN, and YY1 being phenotypes of skeletal muscle atrophy; FBXO32 and TRIM63 were indicators of protein synthesis." (PMID 39239655, 2024). "The FBXO32 gene, also known as Atrogin-1, plays a role in the development of muscular atrophy." (PMID 39415830, 2024). "Interestingly, FBXO32, previously identified as a skeletal muscle atrophy related gene, is located in this region." (PMID 28639938, 2017). "In addition, we analyzed the expression of two documented effectors of muscular atrophy, namely Fbxo32 (Atrogin-1) and Trim63 (MuRF1)." (PMID 26919175, 2016). "However, several putative downstream effectors of Fbxo32 were regulated similarly to other cases of muscular atrophy." (PMID 20886071, 2010). "Therefore, we measured the expression levels of Trim63 and Fbxo32 in a Dex-induced muscular atrophy model to investigate whether GA suppresses muscular atrophy in skeletal muscle cells." (PMID 37049603, 2023). "Their target genes, including FBXO32 (also known as MAFbx/Atrogin-1), TRIM63 (also known as MuRF1), CTSL, and BNIP3, are commonly upregulated in various models of skeletal muscle atrophy, and their upregulation accelerates protein degradation." (PMID 38540418, 2024).
Sepsis (32 papers, 2008 to 2026). Sepsis is defined as life-threatening organ dysfunction caused by a dysregulated host response to infection. "Accordingly, sepsis‐induced reduction in Myh4 expression and induction of Trim63/MuRF1 and Fbxo32/Atrogin1 expression was reversed by BMS‐345541." (PMID 31441598, 2020). "In order to investigate if the atrophy program is activated in skeletal muscle during sepsis, we quantitated the expression of Fbxo30, Fbxo32, and Trim63 in both muscles of sham and CLP mice." (PMID 31441598, 2020). "Fbxo30, Fbxo32, and Trim63 expression was increased in both muscles of septic mice, compared with sham controls, indicating that sepsis leads to an activation of the atrophy program in muscle." (PMID 31441598, 2020). "The Atrogin1/Fbxo32 and MuRF1/Trim63 protein content increased during sepsis in tibialis anterior and BMS‐345541 attenuated this response." (PMID 31441598, 2020). "Ubiquitin-proteasome system markers Fbxo32 and Trim63 mRNA were also comparably affected by sepsis in both groups of lean mice." (PMID 31262340, 2019). "In another study, PGC1β mRNA expression in mice and rats was found to be decreased in response to sepsis and dexamethasone, where both conditions induce ubiquitin mediated proteolysis through up-regulation of Fbxo32 and Trim63 expression." (PMID 28860475, 2017). "However, the sepsis‐induced upregulation of atrophy markers (Fbxo32, Trim63, Ubc, Ubb) was further increased in the Low‐LCT and High‐LCT groups, while expression of myostatin (Mstn) was higher only in the Low‐LCT group." (PMID 41365288, 2025). "Besides the atrophy markers Trim63/MuRF1, Fbxo32/Atrogin‐1, and Fbxo30/MuSA1 (all induced >5‐fold by sepsis, P < 0.001) the expression of Spsb1 was significantly increased after 24 and 96 h of sepsis (24 h: 20‐fold; 96 h: 34‐fold, P < 0.001)." (PMID 37209006, 2023). "Spsb1 knockdown attenuated sepsis‐induced increases in Trim63 and Fbxo32 expression." (PMID 37209006, 2023). "Fbxo32 and Trim63 levels increased in the TA after 24, 48, and 96 h of sepsis." (PMID 31660704, 2019). "Fbxo32 (atrogin‐1) and Trim63 (MuRF1) mRNA levels increased in the DIA after 24 and 96 h of sepsis." (PMID 31660704, 2019).